KRT16 (keratin 16)
Diseases named in the same sentence as KRT16 in open-access papers (continued):
Sharing a sentence is not in itself a finding about the gene and the disease.
melanoma (10 papers, 2008 to 2025). A malignant, usually aggressive tumor composed of atypical, neoplastic melanocytes. "Therefore, we have decided to examine the association of GLI proteins and their targets, S100A7 and KRT16, in melanoma tissues and investigate their association with the level of immune cell infiltration in melanoma." (PMID 38892279, 2024). "We found that stronger expression of KRT16 indeed corresponds to stronger expression of S100A7 in our clinical melanoma samples." (PMID 38892279, 2024). "We present here for the first time that S100A7 and KRT16 are transcriptional targets of GLI proteins in melanoma." (PMID 38892279, 2024). "LogFC values and expression patterns of KRT17 closely follow those of KRT16 in all seven melanoma cell lines." (PMID 36139698, 2022). "In the present study, we found that KRT16 is overexpressed in primary melanoma compared to metastatic melanoma and showed significant difference in different T stage and pathological stage." (PMID 33441834, 2021). "Thus far, 8 out of 21 GLI targets we chose to validate—KRT16, S100A9, SOX9, BIRC7, EBI3, FLG, SAMMSON and SPRY2—were already implicated in melanoma pathogenesis." (PMID 36139698, 2022). "Expression profiles of FABP5, IVL, KRT6A, KRT15, KRT16, and TIMP2 provide clues of prognostic implications, which might help us evaluate malignant potential of nevus and underlying carcinogenesis progress from melanocytic nevus to melanoma." (PMID 32934956, 2020). "Transcription profiles of FABP5, IVL, KRT6A, KRT15, KRT16, and TIMP2 provided clues of prognostic implications, which might help us evaluate malignant potential of nevus and underlying carcinogenesis progress from melanocytic nevus to melanoma." (PMID 32934956, 2020). "Before using clinical melanoma samples, we successfully validated KRT16 and S100A7 as GLI targets on different in vitro models of melanoma cell lines, as their expression was strongly upregulated upon overexpression of all three GLI proteins." (PMID 38892279, 2024). "Moreover, the levels of KRT16 expression may discriminate metastasis from primary melanoma." (PMID 32934956, 2020). "Further, alterations in the expression profiles of FABP5, IVL, KRT6A, KRT15, KRT16, and TIMP2 were significantly associated with worse prognosis, indicating that these hub genes may participate in the aggressive transformation from a nevus to malignant melanoma." (PMID 32934956, 2020). "From this, we identified a panel of 6 genes, ALDH1A1, HSP90AB1, KIT, KRT16, SPRR3 and TMEM45B whose expression values discriminated metastatic from primary melanoma (87% classification accuracy)." (PMID 29229936, 2017). "We find that primary basal cell carcinomas, squamous cell carcinomas and thin melanomas express dramatically higher levels of many genes, including SPRR1A/B, KRT16/17, CD24, LOR, GATA3, MUC15, and TMPRSS4, than metastatic melanoma." (PMID 18442402, 2008). "The enrichment of these categories reflects the dysregulation of transcriptional programs typical of keratinocytes (e.g., SPRR1/2/3, KRT10/KRT16, LOR, IVL, EVPL, SCEL, TGM1/TGM3, CERS3, ACER1, DSP) and, above all, the epithelial crosstalk that influences melanoma biology." (PMID 41465101, 2025). "In addition, survival curves indicated that six hub genes, including FABP5, IVL, KRT6A, KRT15, KRT16, and TIMP2, were significant prognostic signatures for CM and of significant value to predict transformation from nevi to melanoma." (PMID 32934956, 2020). "Importantly, there was a negative correlation between the expression of KRT16 and the infiltration of CD8+ T cells, CD4+ T cells, macrophages, neutrophils, and dendritic cells, which is consistent with previous findings and might provide insights into the immunotherapy of melanoma patients." (PMID 33441834, 2021).
Palmoplantar keratoderma (10 papers, 2008 to 2025). Abnormal thickening of the skin of the palms of the hands and the soles of the feet. "Mutations in Krt17 and Krt16 are associated with Palmoplantar Keratoderma (PPK) lesions (i.e. abnormal thickening of palm skins) in humans, and mice that lack the Krt16 gene develop spontaneous lesions resembling human PPK." (PMID 31968015, 2020). "Oxidative stress has been linked previously to palmoplantar keratoderma associated with Keratin 16 (K16) mutations, and the use of SFN (Sulforaphane), a natural isothiocyanate compound found in cruciferous vegetables, rescued the palmoplantar keratoderma phenotype in krt16−/− mice." (PMID 29523849, 2018). "However, the disease-causing variants observed in type I keratins (KRT9, KRT10, KRT13, KRT14, KRT16, KRT17) occur mostly in the rod domains (1A, 1B and 2B), except in the case of palmoplantar keratoderma." (PMID 34991727, 2022).
Hyperkeratosis (9 papers, 2008 to 2025). Hyperkeratosis is a histopathological term defining a thickened stratum corneum and may be present in many different skin conditions, with many possible overlaps. "Supportively, strong KRT16 immunostaining was observed in the suprabasal epidermal layer of KO skin, particularly in the area with hyperkeratosis." (PMID 37809094, 2023). "The histopathological alterations in the footpad skin of the affected Rottweiler were comparable to the changes seen in footpad hyperkeratosis of FAM83G mutant Irish Terriers and Kromfohrländer dogs and KRT16 mutant Dogues de Bordeaux." (PMID 32344723, 2020). "However, upregulated FLG reflects hyperkeratosis, while ALOX12B, ALOXE3, and KRT16 are wound-activated genes in the oral mucosa, suggesting an ongoing wound repair process." (PMID 34506598, 2021).
squamous cell carcinoma (8 papers, 2008 to 2023). A carcinoma arising from squamous epithelial cells. "KRT16 is typically and strongly expressed in squamous cell carcinomas of different sites." (PMID 30782177, 2019). "Meanwhile, immunohistochemical staining of KRT14 and KRT16 in PM and MM were mostly negative, and the positive distribution contributed to the diagnosis of poorly differentiated squamous cell carcinoma." (PMID 33240619, 2020).
lung adenocarcinoma (7 papers, 2021 to 2024). A carcinoma that arises from the lung and is characterized by the presence of malignant glandular epithelial cells. "For example, TFAP2A enhances the metastatic ability of lung adenocarcinoma through the miR-16/TFAP2A/PSG9/TGF-β axis and promotes the progression of lung adenocarcinoma through epithelial–mesenchymal transition (EMT) by inducing the expression of KRT16." (PMID 39695171, 2024). "Recent studies demonstrate that keratin 16 possesses oncogenic activity to promote the tumorigenesis of lung adenocarcinoma and is a predictive factor of poor patients’ prognosis." (PMID 39739089, 2024). "TFAP2A induced Keratin-16 overexpression, promotes tumorigenicity in lung adenocarcinoma and metastasis via epithelial-mesenchymal transition (EMT)." (PMID 36123698, 2022). "Importantly, keratin 16 overexpression promotes lung adenocarcinoma metastasis by stabilizing the structural protein vimentin, which is essential for metastasis driven by keratin 1644." (PMID 39739089, 2024). "As observed in the TCGA lung adenocarcinoma analysis, the paired PDS established from the other three patients with adenocarcinoma (empty black symbols; 19LuCa05, 19LuCa06, and 19LuCa08) revealed a lower expression of KRT16 between tumor and normal tissues." (PMID 38067281, 2023).
cervical carcinoma (6 papers, 2008 to 2025). A carcinoma arising from either the exocervical squamous epithelium or the endocervical glandular epithelium. "We performed a similar analysis on our RNA-seq analysis and identified several genes that are also implicated in cervical cancer and HPV infection, including Krt16 (up), Krt6a (up), Hmox1 (up), and Krt15 (down)." (PMID 41165329, 2025). "Based on the HPA, keratin 16 is enhanced in cervical cancer and it is a poor prognostic biomarker for pancreatic cancer." (PMID 36949761, 2023). "The similar mode of regulation of KRT16, FAM129A and HKDC1 genes by ER stress and dysfunctional mitochondrial respiration was observed in cervical carcinoma HeLa cells." (PMID 29420561, 2018). "These genes, particularly CEBPD, SLPI, KRT16, and NOTCH1, may serve as potential biomarkers at the mRNA level for the course of cervical cancer development, and warrant further study as it relates to understanding HPV-dependent carcinogenesis." (PMID 34944802, 2021).
inflammatory skin disease (6 papers, 2014 to 2023). Inflammatory skin disorders covers a broad category that includes many conditions ranging in severity, from mild itching to grave medical health complications These disorders are common in people of all ages and races. "The spinous cluster also expressed KRT6A, KRT6C, and KRT16, which have been associated with inflammatory skin diseases and barrier dysfunction." (PMID 37675143, 2023). "Aberrant KRT16 expression has been implicated in the as a number of inflammatory skin diseases as well as breast and pancreatic cancer." (PMID 32151264, 2020). "Consistent with our FSHD findings, KRT16 and S100A8 are also up-regulated together in inflammatory skin disorders; additionally, the pattern of increased S100A8 with decreased PROC is seen here in FSHD as well as in IBD and several other chronic inflammatory disorders." (PMID 33228131, 2020).
acne (4 papers, 2016 to 2024). An inflammatory process of the sebaceous glands which is characterized by comedones, nodules, papules and/or pustules on the skin. "Concurrently, treating human HaCaT cells with IL-13 to activate IL-13RA1 signaling resulted in dysregulation of KRT16, KRT17, and FLG expression, which are associated with hyperproliferation-associated phenotypes in acne." (PMID 39143467, 2024). "Moreover, this study noted a reduction in IL-1 alpha and keratin 16, suggesting that CBD may have potential in enhancing the clinical outcomes of acne scarring." (PMID 38904694, 2024).
metastatic melanoma (4 papers, 2008 to 2024). A melanoma that has spread from its primary site to another anatomic site. "KRT16 is linked to better outcomes in metastatic melanoma, while low levels of S100A8/A9 correlate with advanced disease stages." (PMID 39766071, 2024). "KRT16, a regulator of innate immunity in the skin, seemed to be significantly downregulated in metastatic melanoma and was also found to be the highest discriminator between prognostic and metastatic melanoma." (PMID 36139698, 2022).
oral squamous cell carcinoma (4 papers, 2019 to 2025). "In addition, microRNA-365-3p targeted ETS homologous factor, a KRT16 transcription factor, to suppress migration, invasion, and metastasis in oral squamous cell carcinoma cells by suppressing KRT16." (PMID 35037835, 2022). "Abnormal expression of keratins is reported in cancer cells and the keratin profiling of oral squamous cell carcinoma exhibited higher expression of keratins such as KRT6, KRT16, and KRT17." (PMID 36393868, 2022).
atopic dermatitis (3 papers, 2015 to 2025). "KRT16 and COL6A6 were up-regulated in atopic dermatitis skin while the rest were down-regulated." (PMID 26717000, 2015).
pancreatic cancer (3 papers, 2017 to 2023). "Among the five top DEGs, overexpression of SERPINB5, HOXA10 and KRT16 at the mRNA level has previously been reported in pancreatic cancer." (PMID 28418924, 2017).
skin cancer (3 papers, 2013 to 2019). "Among the upregulated genes in SCC were several genes known to be involved in keratinocyte differentiation and skin cancer, including keratins (e.g. KRT16, KRT17 and KRT6), matrix metalloproteinases (MMPs), S100 molecules and small proline-rich proteins (SPRRs)." (PMID 23379751, 2013). "The rabbit skin tumours induced via blood infection displayed decreased expression of SLN, TAC1, MYH8, PGAM2, and APOBEC2 and increased expression of SDRC7, KRT16, S100A9, IL36G, and FABP9, as seen in tumours induced by local infections." (PMID 31340720, 2019). "KRT17 together with KRT16 and KRT6 are involved in keratinocyte differentiation and skin cancer." (PMID 28852586, 2017).
bladder cancer (2 papers, 2020 to 2024). "Using a combination of the two drugs, several proteins associated with the basal subtype of bladder cancers were consistently decreased within both cell lines such as KRT1, KRT14, KRT16, P63, and TFAP2A." (PMID 32822399, 2020). "The same study found TRIM29 gene expression to be correlated to KRT5, KRT14, KRT6A, and KRT16 expression using The Cancer Genome Atlas (TCGA) RNA sequencing data from multiple tumor types, including basal subtype bladder cancers." (PMID 32822399, 2020). "However, a combined treatment of TG and PD resulted in a consistent decrease of several proteins associated with the basal subtype of bladder cancers (KRT1, KRT14, KRT16, P63, and TFAP2A)." (PMID 32822399, 2020).
dermatitis (2 papers, 2020 to 2023). An inflammatory process affecting the skin. "The HFD decreased mRNA expression of hyperproliferation-associated keratin 16 induced by imiquimod, and increased that of cell cycle inhibitor CDKN1A in imiquimod-induced dermatitis." (PMID 37762500, 2023). "Oral administration of Bifidobacterium breve CCFM683 reduced keratin 16 expression in imiquimod-induced dermatitis with increased concentrations of several bile acids in the colon, indicating involvement of certain bile acids in down-regulation of keratin 16 expression." (PMID 37762500, 2023). "The HFD decreased mRNA expression of IL-17A, IL-17F, IL-22, TNF-α, IL-1β, CXCL1, CXCL2, and keratin 16, and increased mRNA expression of TGF-β1 and CDKN1A in imiquimod-induced dermatitis." (PMID 37762500, 2023). "HFD reduced mRNA levels of IL-17A, IL-17F, IL-22, IL-1β, tumor necrosis factor (TNF)-α, CXCL1, CXCL2, and keratin 16 and increased those of transforming growth factor (TGF)-β1 and cyclin-dependent kinase inhibitor 1A in imiquimod-induced dermatitis." (PMID 37762500, 2023).
esophageal cancer (2 papers, 2023). A primary or metastatic malignant neoplasm involving the esophagus. "Interestingly, keratin 16 is another esophagus tissue-specific protein that we found overexpressed in esophageal cancer." (PMID 37444412, 2023). "Of the top 20 genes whose expression most correlated with ZNF750 expression in esophageal cancer, 10 were epidermal differentiation and keratinization-related genes, such as LYPD3, KRT6A, KRT16, and IVL." (PMID 37365152, 2023).
lung carcinoma (2 papers, 2021 to 2024). "Mechanistic studies using transwell assays and xenograft mouse models demonstrated that KRT16 knockdown reduces lung cancer metastasis in both in vitro and in vivo settings." (PMID 39830981, 2024).
lymph node metastases (2 papers, 2019 to 2025). "High KRT16 expression was found to be associated with more lymph node metastasis and poor clinical survival in our study." (PMID 30782177, 2019). "OSCC patients with higher KRT16 expression often present poor pathologic differentiation, advanced stage, lymph node metastases, and poor survival." (PMID 41180476, 2025). "This analysis revealed that patients with high KRT16 expression were correlated with significantly poorer overall survival and more lymph node metastasis." (PMID 30782177, 2019).
oral cancer (2 papers, 2019 to 2023). "In conclusion, we discovered a novel regulatory cascade of miR-365-3p/EHF/KRT16/β5-integrin/c-Met signaling regulating oral cancer metastasis, cancer stemness, and drug resistance." (PMID 30782177, 2019). "Some of the DEGs common to OLP and oral cancer include KRT4 (down-regulated) and KRT16, KRT17, KRT10, and KRT75 (up-regulated)." (PMID 38234400, 2023). "To investigate whether KRT16 could affect cancer stemness of OSCC, we enriched the oral cancer stem-like cells from both OC-3-IV and C9-IV3 sublines by sphere-forming assay." (PMID 30782177, 2019).
ovarian carcinoma (2 papers, 2021 to 2025). A malignant neoplasm originating from the surface ovarian epithelium. "OV_sBRCA1 samples were, in turn, characterized by the upregulation of KRT16, which is linked to migration, invasion, metastasis, and cancer stemness in ovarian cancer cells." (PMID 33525353, 2021). "For instance, in BRCA1-mut ovarian cancer, KTR14, KRT16, CXCL9, and CFD were highly upregulated (more than 4-fold change), and in BRCA2-mut ovarian cancers, TSPAN7 and CDKN2C were clearly upregulated (more than 2-fold change)." (PMID 40647506, 2025).
cervical dysplasia (1 paper, 2021). "Five out of ten consistently upregulated genes (CEBPD, KRT16, SLPI, RPS29, and PPL) were also increased in cervical dysplasia." (PMID 34944802, 2021). "Unlike CEBPD, SLPI, KRT16, and RPS29, NOTCH1 expression in these cell lines did not match the increase seen in cervical dysplasia and cancer samples in silico." (PMID 34944802, 2021).
colon carcinoma (1 paper, 2018). "As verified by RT-qPCR, a dysfunction of mitochondrial respiration chain and ER stress resulted in a partially ATF4-dependent stimulation of KRT16, FAM129A and HKDC1 expression in the HCT116 colon carcinoma cell line." (PMID 29420561, 2018).
conjunctivitis (1 paper, 2023). Inflammation of the conjunctiva of the eye. "Krt16, a marker of keratinocyte activation, was elevated, suggesting that epithelial damage is an important factor in causing the pathophysiology of conjunctivitis." (PMID 36626228, 2023).
dental caries (1 paper, 2018). The decay of a tooth, in which it becomes softened, discolored, and/or porous. "Due to the low number of frequent missense SNPs in KRT16 and KRT17 in our cohorts, the present study did not allow us to make any conclusion on the potential genetic association between variants in these two genes and dental caries experience." (PMID 29357356, 2018).
diabetes (1 paper, 2015). "Thus, Krt16 was inhibited in keratinocytes in diabetic wounds due to the up-regulation of Smad2 expression, which is indeed increased in diabetes." (PMID 26428860, 2015).
food allergy (1 paper, 2025). Gastrointestinal disturbances, skin eruptions, or shock due to allergic reactions to allergens in food. "In pediatric patients with AD, KRT5, KRT14, KRT16, FLG breakdown products, and AD clinical severity were predictive of concomitant food allergy." (PMID 40141720, 2025).
Harlequin ichthyosis (1 paper, 2022). Harlequin ichthyosis (HI) is the most severe variant of autosomal recessive congenital ichthyosis (ARCI; see this term). "Interestingly, some of these genes, i.e. KRT1, KRT9, KRT16, DSG1, DSC2 and JUP, are mutated in hereditary PPKs, while the ABCA12 gene is defective in harlequin ichthyosis characterized by the loss of the skin lipid barrier." (PMID 35854363, 2022).
head and neck squamous cell carcinoma (1 paper, 2024). A squamous cell carcinoma that arises from any of the following anatomic sites: lip and oral cavity, nasal cavity, paranasal sinuses, pharynx, larynx, and salivary glands. "KRT6 and KRT16 are proposed as potential biomarkers for diagnosing head and neck squamous cell carcinoma (HNSCC)." (PMID 38398015, 2024).
injury (1 paper, 2024). Damage inflicted on the body as the direct or indirect result of an external force, with or without disruption of structural continuity. "Hericium erinaceus mycelia could regulate epidermal differentiation by decreasing the expression of Krt16 and Krt6b, thus alleviating ethanol-induced chronic gastric injury in mice." (PMID 38213743, 2024).
meningioma (1 paper, 2023). A generally slow growing tumor attached to the dura mater. "Here, TRAF7 meningiomas expressed a high number of specific DEGs, including RAPGEFL1, KRT16, KRT6A, IL1RL1, NOS1, and others." (PMID 36937440, 2023). "In agreement, TRAF7-deficient MEFs also had an increased expression of several investigated TRAF7 meningioma signature genes, including IL1RL1, KRT16, KRT6A, and AQP3." (PMID 36937440, 2023).
nasal polyps (1 paper, 2024). "In this context, KRT16 is proposed to regulate cell proliferation, repair, and immune responses via glycolysis, closely linking it to the tissue remodeling processes characteristic of nasal polyps." (PMID 39830981, 2024).